MMP8 (matrix metallopeptidase 8)
Diseases named in the same sentence as MMP8 in open-access papers (continued):
Sharing a sentence is not in itself a finding about the gene and the disease.
gestational diabetes (3 papers, 2020 to 2024). Carbohydrate intolerance first diagnosed during pregnancy. "Further studies will be needed to assess the role of IGFBP-1, phIGFBP-1 and MMP-8 in maternal metabolism throughout the entire course of pregnancy, both in normal weight women and in relation to clinical manifestations like gestational diabetes." (PMID 32923723, 2020). "In a recent study of non-pregnant women with a history of gestational diabetes, a weak correlation was observed between MMP-8 and CRP, indicating that MMP-8 may be involved in modulating inflammation." (PMID 32923723, 2020).
head and neck squamous cell carcinoma (3 papers, 2008 to 2019). A squamous cell carcinoma that arises from any of the following anatomic sites: lip and oral cavity, nasal cavity, paranasal sinuses, pharynx, larynx, and salivary glands. "In line with this, elevated levels of MMP8 expression have been observed in head and neck squamous cell carcinomas." (PMID 18366705, 2008).
Hepatitis (3 papers, 2019 to 2021). Inflammation of the liver. "MMP-8, also referred to as collagenase-2, is considered to play an essential role in the development of hepatitis in TNF-induced conditions." (PMID 31083413, 2019). "In TNF-induced lethal hepatitis, MMP-8-deficient mice showed impaired leukocyte influx and neutrophil-specific chemokine release implicating that, rather than influencing the hepatitis-induced hepatocyte necrosis as previously thought, MMP-8 plays a pivotal role in regulating acute inflammation." (PMID 32414178, 2020).
influenza (3 papers, 2021 to 2024). An acute viral infection of the respiratory tract, occurring in isolated cases, in epidemics, or in pandemics; it is caused by serologically different strains of viruses (influenzaviruses) designated A, B, and C, has a 3-day incubation period, and usually lasts for 3 to 10 days. "Area under the curve (AUC) analysis of ROC showed that LCN2, BPI, ELANE and MMP8 expression represented severe influenza infection." (PMID 33448094, 2021). "Specially, it has been reported recently that originally identified as neutrophil collagenase, MMP8 was elevated after influenza infection." (PMID 33448094, 2021). "Among them, some proteins related to specific neutrophils granules, such as bactericidal/permeability‐increasing (BPI) protein and matrix metalloproteinase‐8 (MMP8) protein, were generally more abundant in relative severe influenza cases." (PMID 33448094, 2021). "The concentrations of the RETN, MMP8, LCN2, ELANE and BPI in plasma tended to be higher in influenza patients than healthy donors." (PMID 33448094, 2021).
ischemia (3 papers, 2018 to 2026). A hypoperfusion of the BLOOD through an organ or tissue caused by a PATHOLOGIC CONSTRICTION or obstruction of its BLOOD VESSELS, or an absence of BLOOD CIRCULATION. "Mmp8 and Mmp9 became overexpressed very soon after coronary occlusion (6 h), peaking at day one of ischemia with a Log2FoldChange around 4 and returning to control levels at day seven of ischemia." (PMID 36555255, 2022).
liver cancer (3 papers, 2019 to 2023). An epithelial or non-epithelial malignant neoplasm that arises from the liver. "However, in liver cancer cells MMP8 activates PI3K/Akt/Rac1 signalling pathway leading to increased aggressiveness." (PMID 34059618, 2021). "Recombinant NDV-expressing MMP8 (NDV-MMP8) was constructed, and intratumoral injection efficiently degraded ECM, enhanced virus spread, and induced tumor regression in liver cancer xenograft mouse models." (PMID 37629483, 2023).
Neonatal sepsis (3 papers, 2017 to 2025). Systemic inflammatory response to infection in newborn babies. "We have previously demonstrated that elevated MMP8 and interleukin-8 and low platelet counts were associated with a higher mortality risk from neonatal sepsis." (PMID 40655143, 2025). "AF-MMP-9 (p = 0.006), MPO (p = 0.011), HNE (p = 0.034), and MMP-8/TIMP-1 molar ratio (p = 0.034) were associated with blood culture positive neonatal sepsis when the data were adjusted by gestational age at delivery (data not shown)." (PMID 28167848, 2017). "MMP-8 has been identified as a biomarker of neonatal sepsis." (PMID 36639750, 2023). "Lastly, we identified genes that reliably distinguished neonatal sepsis endotypes, with the top two being cathepsin G (CTSG) and matrix metalloprotease 8 (MMP8)." (PMID 40655143, 2025).
osteonecrosis (3 papers, 2016 to 2026). A none disease characterized by death of bone tissue due to a lack of blood supply. "Enhanced MMP-8 immunoreactivity was observed in 61% of medication-related osteonecrosis vs. 38% in non-medication-related biopsies (p = 0.002), and MMP-8 was especially expressed alongside actinomycotic lesions (57% vs. 34%; p < 0.001)." (PMID 41940898, 2026).
pancreatic cancer (3 papers, 2019 to 2023). "The intracellular C-terminus of ephrin-B1, that is required for invasion of pancreatic cancer cells in vitro and in vivo in mice, was shown to regulate the release of MMP8 from these cells via activation of the cell trafficking regulator, Arf1." (PMID 31514474, 2019). "MMP-8 expression in pancreatic cancer has not been studied extensively." (PMID 35328734, 2022). "Additionally, no MMP8 gene expression was found in stellate cells—building blocks of the ECM in pancreatic cancer." (PMID 31514474, 2019).
preeclampsia (3 papers, 2019 to 2022). Preeclampsia is a hypertensive disorder of pregnancy that is characterized by new-onset hypertension with proteinuria presenting after 20 weeks of gestation, and depending on mild or severe forms may initially present with severe headache, visual disturbances, and hyperreflexia. "In our study, there was an increase in circulating levels of MMP8 expression at TOD in women with preeclampsia cases compared to healthy controls." (PMID 30976066, 2019). "Similarly, there was no statistical significance at each time-point when comparing expression of calprotectin, MPO and MMP8 in preterm preeclampsia versus term preeclampsia." (PMID 30976066, 2019). "In healthy pregnancies, some MMPs, for example, MMP8 and MMP9, are upregulated in uterine epithelial cells, and preeclampsia." (PMID 32296081, 2020). "A regression model using five RNAs selected for ‘pregnancy hypertension’ (preeclampsia and gestational hypertension) yielded good predictive power with an AUC of 0.86, and like the present study, their proposed RNA panel included NAMPT (the remaining markers were MMP8, SRPK1, S100A9, and S100A8)." (PMID 35741140, 2022).
systemic inflammatory response syndrome (3 papers, 2017 to 2022). SIRS is a serious condition related to systemic inflammation, organ dysfunction, and organ failure. "Furthermore, multiple templates were employed to model a VHH against matrix metalloproteinase 8 (MMP8) linked to several pathological conditions, e.g., lethal hepatitis and the systemic inflammatory response syndrome." (PMID 35409081, 2022).
ulcers (3 papers, 2019 to 2022). "Particularly, all the collagenases (MMP-1, MMP-8 and MMP-13) are co-expressed, which have been shown to play roles of collagenases in wounds and ulcers." (PMID 35444067, 2022).
adenoma (2 papers, 2024 to 2025). A neoplasm arising from the epithelium. "Correspondingly, patients with invasive adenomas had elevated serum MMP‐8 levels and lower TIMP‐1 levels, suggesting that these molecules serve as valuable markers for assessing IPA invasion." (PMID 39688352, 2024). "Stool fibrinogen, MMP-8, MMP-9, PGRP-S, haptoglobin, and myeloperoxidase emerge as promising biomarkers for distinguishing CRC/advanced adenomas/healthy stools, meeting or outperforming current yardsticks." (PMID 41033463, 2025). "Stool fibrinogen, MMP-9, hemoglobin, MMP-8, and PGRP-S were the top 5 stool proteins with the highest accuracy for distinguishing advanced adenoma from HC, with stool fibrinogen topping the list with a receiver operating characteristic area under the curve value of 0.86." (PMID 41033463, 2025).
adrenocortical carcinoma (2 papers, 2021). "After surgery, MMP-8 and MMP-9 levels decreased significantly in patients with adrenocortical carcinoma, whereas the decrease in these MMPs in patients with benign tumors was not significant." (PMID 33578890, 2021). "High levels of MMP-8 and MMP-9 levels were found in patients with adrenocortical cancer, but were not indicative in differing malignancy." (PMID 33578890, 2021). "However, MMP-8 and MMP-9 levels were not increased in patients with inoperable adrenocortical cancers while MMP-1 level was not increased in patients with either benign or malignant adrenal tumors." (PMID 33578890, 2021).
alcohol (2 papers, 2017 to 2021). "We investigated 13 SNPs to explore the relation of polymorphisms of the genes MMP-3 and MMP-8 to alcohol-induced ONFH risk in Chinese males." (PMID 28445942, 2017).
aortic aneurysm (2 papers, 2013 to 2022). A ruptured aneurysm located in the wall of the proximal portion of the descending aorta proceeding from the arch of the aorta. "Of note, plasma MMP8 was not increased in patients with uncomplicated aortic aneurysm, suggesting that aortic dilation per se is not sufficient to significantly increase the circulating levels of MMP8 in this patient population." (PMID 23442769, 2013). "As plasma MMP8 and MMP9 were similar in patients with uncomplicated aortic aneurysm and in patients with other unspecific diagnoses having a regular aortic size, aortic dilation per se does not appear as a major determinant of plasma MMP8 and MMP9 in the selected population of patients." (PMID 23442769, 2013).
astrocytoma (2 papers, 2015 to 2024). "An elevation in the protein levels of MMP1, MMP2, MMP3, and MMP8 was observed in astrocytoma samples, whereas a decrease in the amount of these proteins was noted in the glioblastoma group compared to the control group." (PMID 38474106, 2024). "An increase in the protein levels of MMP1, MMP2, MMP3, and MMP8 was observed in astrocytoma samples, while a reverse trend was noted, with a decrease in the amount of these proteins in the glioblastoma group when compared to the control group." (PMID 38474106, 2024). "Low levels of MMP8 amplification were observed in all tumors, with astrocytomas showing a significant change compared to CTRL (p = 0.017) and MNG (p = 0.035)." (PMID 38474106, 2024). "Similar results were obtained in astrocytomas: specifically, in the genes MMP3, MMP8, MMP10, TIMP2, and TIMP4." (PMID 38474106, 2024).
bacteremia (2 papers, 2021 to 2025). "Future studies need to evaluate the pathogenetic role of MMP-8 and MMP-8/TIMP-1 in bacteremia which might open possibilities for pharmacological therapies to control their activation in bacteremia." (PMID 34043679, 2021). "Thus, the study cannot evaluate how MMP-8, TIMP-1 and MMP-8/TIMP-1 would perform in MRSA bacteremia." (PMID 34043679, 2021). "However, this trend declined during follow-up and at day 28 only high Pitt bacteremia scores were connected to elevated MMP-8 levels." (PMID 34043679, 2021). "High Pitt bacteremia scores were associated to higher MMP-8 (p<0.05) on day 28 but TIMP-1 level was not affected by the Pitt bacteremia score." (PMID 34043679, 2021). "First, we included only MS-SAB patients and MMP-8 and TIMP-1 concentrations were measured in relation to bacteremia onset regardless of severity of illness, PITT bacteremia score or ICU admission." (PMID 34043679, 2021).
bronchiolitis obliterans (2 papers, 2008 to 2025). "Taghavi and coworkers have described increased MMP-9 and MMP-8 levels in bronchiolitis obliterans from lung transplant patients." (PMID 18700005, 2008). "Furthermore, proteolytic enzymes commonly associated with extracellular matrix degradation and neutrophil migration, including metalloproteinases (such as MMP9 and MMP8), have been identified at elevated levels in patients affected by bronchiolitis obliterans syndrome (BOS), a form of CLAD." (PMID 40283490, 2025).
bronchitis (2 papers, 2009 to 2017). An acute or chronic inflammatory process affecting the bronchi. "The levels of MMP-8 in bronchitis/COPD after stopping of smoking at 3 months were still much higher than in non-smokers as measured in our recent study." (PMID 19473482, 2009).
Cerebral ischemia (2 papers, 2018 to 2019). Restriction of arterial blood supply to the brain associated with insufficient oxygenation to support the metabolic requirements of the tissue. "Our previous studies demonstrated that MMP-8 modulates neuroinflammation in cultured microglia, septic mice, and cerebral ischemia." (PMID 30470240, 2018). "Moreover, M8I inhibited microglial activation and TNF-α expression in the brain of mice with systemic inflammation and cerebral ischemia, corroborating the findings through MMP-8 knockdown experiments." (PMID 30470240, 2018). "Both MMP-8 and MMP-12 have been reported as critical factors for brain damage in cerebral ischemia in animal studies." (PMID 30777092, 2019).
cerebral malaria (2 papers, 2021 to 2025). A sequestration of Plasmodium falciparum in the brain, which can cause coma and/or seizures. "Tissue inhibitor of metalloproteinases 1 is the most upregulated protein in cerebral malaria, which along with elevated MMP8 and MMP9 transcription, underscores the importance of the metalloproteinase pathway in central nervous system pathophysiology." (PMID 40383794, 2025). "MMP8, IL1R2, and ARG1 transcription is higher across cerebral malaria, severe malarial anemia, and concurrent cerebral malaria and severe malarial anemia, indicating a shared inflammatory signature." (PMID 40383794, 2025).
cholesteatoma (2 papers, 2016 to 2025). A pathologic process characterized by the proliferation of keratinizing squamous epithelium resulting in the accumulation of keratin and cells in the middle ear and/or mastoid. "TREM2 amplifies the inflammatory response of the TLR4 signaling pathway, promoting the secretion of MMP-2 and MMP-8 and the excessive activation of osteoclasts, thereby facilitating bone destruction induced by acquired cholesteatoma." (PMID 40242752, 2025). "In human acquired cholesteatoma, the expression of proinflammatory cytokines (IL-1β, TNF-α and IL-6) and matrix metalloproteinases (MMP-2, MMP-8 and MMP-9) were up-regulated, and their expression levels were positively correlated with TREM-2 expression." (PMID 27934908, 2016). "Therefore, the MMP expression levels were tested using Real-time PCR, and the results revealed that the expression levels of MMP-2 (p < 0.01), MMP-8 (p < 0.001) and MMP-9 (p < 0.01) were significantly increased in human acquired cholesteatoma (n = 10) compared with the normal skin (n = 10)." (PMID 27934908, 2016).
chronic bronchitis (2 papers, 2009 to 2011). A type of chronic obstructive pulmonary disease characterized by chronic inflammation in the bronchial tree that results in edema, mucus production, obstruction, and reduced airflow to and from the lung alveoli. "Several MMPs including MMP-8, MMP-9 and MMP-12 have been associated with COPD; in our recent study only the levels of MMP-8 were higher in chronic bronchitis compared to asymptomatic smokers." (PMID 19473482, 2009). "Sputum neutrophils increased after smoking cessation in patients with chronic bronchitis/COPD, but the levels of FeNO, nitrotyrosine and MMP-8 did not change significantly during the 3 months after smoking cessation in any of the groups." (PMID 19473482, 2009).
chronic granulocytic leukemia (2 papers, 2013 to 2019). "One of the most intriguing MMPs, MMP-8, also known as collagenase-2 or neutrophil collagenase, was long thought to be expressed solely in neutrophil precursors since it has been cloned from RNA extracted from peripheral blood leukocytes of a patient with chronic granulocytic leukemia." (PMID 23365489, 2013).
dengue (2 papers, 2023 to 2024). "A clinical study should be conducted to ascertain whether IL-17A and γδ T cells, as well as other IL-17A-producing cells, neutrophils, and MMP-8, are involved in the pathogenesis of severe dengue in humans." (PMID 37939119, 2023). "MMP-8 may act as a major effector in humans with severe dengue." (PMID 37939119, 2023). "Increased neutrophil counts and a correlation between MMP-8 levels and neutrophilia have been reported in patients with severe dengue; however, MMP-8 has not been reported as an inducer of vascular leakage in other areas of research." (PMID 37939119, 2023). "Infection also induced neutrophil infiltration in the small intestine, and increased expression of IL-6 and MMP-8 and blockade of TNF-α signaling protected the mice, as demonstrated in a previous severe dengue mouse model using C57/BL6 mice lacking both IFN-α/β and IFN-γ receptors." (PMID 38550855, 2024). "Notably, the α-IL-17A Ab also suppressed MMP-8, but not MMP-3, suggesting that MMP-3 plays less of a role in severe dengue." (PMID 37939119, 2023).
encephalitis (2 papers, 2019 to 2025). An acute inflammatory process affecting the brain parenchyma. "Especially MMP9, MMP8 and MMP3 are vividly upregulated intrathecally in murine encephalitis models, with a potential redundancy of their proteolytic effects." (PMID 40003967, 2025). "The patients with encephalitis had the most significantly increased levels of MMPs in CSF, and MMP-3, MMP-8, and MMP-12 were exclusively increased in this group, whereas MMP-9 in CSF was increased in the patients with VZV meningitis." (PMID 30777092, 2019). "In addition, patients with encephalitis showed pronounced increased levels of MMP-3, MMP-8, and MMP 12 in their CSF compared to controls, indicating an association to the severity of this manifestation." (PMID 30777092, 2019). "In addition, patients with encephalitis had pronounced increased levels of MMP-3, MMP-8, and MMP-12 in their CSF compared to controls, suggesting an association to the severity of this manifestation." (PMID 30777092, 2019).
esophageal cancer (2 papers, 2019). A primary or metastatic malignant neoplasm involving the esophagus. "In regard to esophageal cancer, MMP8 levels were significantly lower in serum samples from early stage patients compared to healthy controls." (PMID 31514474, 2019). "Several studies showed that MMP1 and MMP8 expressions were also elevated in esophageal carcinoma cells; however, these studies did not mention the effect of Arecoline on the muscarinic acetylcholine receptor." (PMID 30925742, 2019).
fibrosarcoma (2 papers, 2016 to 2019). A malignant mesenchymal fibroblastic neoplasm affecting the soft tissue and bone. "MMP8 expression is detected in fibrosarcoma cell lines, but not in the in vivo chorioallantoic membrane (CAM) assay, which is used to study tumor angiogenesis and invasion." (PMID 31514474, 2019).
gastric adenocarcinoma (2 papers, 2019 to 2020). "Next, 10 ERGs associated with prognosis of gastric adenocarcinoma patients are screened out by univariate Cox regression, and 6 pivotal prognostic ERGs (MMP8, MMP11, TFDP3, MYB, F2, and CNTN1) are identified through multivariate Cox regression." (PMID 32309437, 2020). "On the other hand, MMP8 mRNA expression was lower in gastric adenocarcinoma tumors compared to paired healthy tissue." (PMID 31514474, 2019).
gastritis (2 papers, 2017 to 2023). Inflammation of the stomach. "MMP-8 was shown to be upregulated in gastric epithelial cells and elevated levels of MMP-8 could be observed in sera from H. pylori associated gastritis patients; however little is known about its regulation and its biological relevance." (PMID 28398251, 2017). "The results indicated that in H. pylori-positive patients with gastritis, the serum levels of myeloperoxidase, neutrophil elastase, MMP-8, and MMP-9 increased significantly." (PMID 37605137, 2023).
glioblastoma (2 papers, 2019 to 2024). The most malignant astrocytic tumor (WHO grade IV). "Reduced levels of MMP8 were observed when glioblastoma multiforme spheroids were treated with 5-aminolevulinic acid-photodynamic therapy." (PMID 31514474, 2019).